CSF1R (colony stimulating factor 1 receptor)
Diseases named in the same sentence as CSF1R in open-access papers (continued):
Sharing a sentence is not in itself a finding about the gene and the disease.
glioma (continued). "In a glioma mouse model, a tyrosine kinase inhibitor PLX3397 that targets CSF-1R, c-Kit and Flt3 blocks tumor progression through depolarizing M2 phenotype of TAMs and impairing their pro-tumor function." (PMID 34359674, 2021). "Inhibition of CSF-1R by PLX3397 was reported to reduce tumor cell proliferation and glioma progression in a PDGF-B-driven proneural glioma mouse model, although having no direct effect on cultured GBM cells." (PMID 30644073, 2019). "In a murine GL261 glioma model, the group also found that treatment with PLX3397, a CSF-1R inhibitor that can cross the blood brain barrier, significantly decreased the proportion of microglia in the TME." (PMID 31396227, 2019). "Several clinical trials are currently testing CSF-1/CSF-1R targeting agents (including the Novartis small-molecule inhibitor BLZ945 and Roche monoclonal antibody RG7155) in, among others, breast cancer, glioma, melanoma, ovarian cancer, and lung cancer." (PMID 31611871, 2019). "One interaction of potential therapeutic interest in glioma is the macrophage proliferation cytokine CSF1 and its cognate receptor CSF1R, which has been extensively validated in pre-clinical studies in glioma along with its potential therapeutic efficacy." (PMID 30041684, 2018). "Trials where anti‐CSF‐1R agents are combined with chemotherapy, immunotherapy, or targeted therapy are still ongoing, with only some very preliminary promising results, but fighting on several fronts could be the way forward in the treatment for aggressive tumors such as high‐grade gliomas." (PMID 29127101, 2017). "For example, a colony stimulating factor-1 receptor (CSF-1R) inhibitor is used to target TAM and thus results in a robust decrease in tumor volume along with improved survival in preclinical trials of glioma." (PMID 27793010, 2016). "CSF1-R is overexpressed by MDSC and TAMs in human glioma and its expression was shown to correlate with glioma grade." (PMID 28003994, 2016). "Dual CSF1R/PI3Kγ blockade simultaneously suppresses STAT3-driven signalling, decreases serum sCD163 pharmacodynamic biomarker levels, and is tolerated up to 800 mg daily with reversible transaminase elevation in phase-I glioma cohorts." (PMID 40995359, 2025). "Similarly, Pyonteck and coworkers used a BBB-penetrant colony stimulating factor-1 receptor (CSF-1R) inhibitor BLZ945 with an IC50 of 1 nM to reprogram macrophages into the inflammatory M1 state and block mouse glioma progression." (PMID 41227348, 2025). "Several preclinical studies have demonstrated the value of anti-CD40 agonist treatment in reprogramming GAMs and boosting anti-tumor immunity, e.g. in combination with CSF-1R blockade, IL-6 inhibition or with the microtubule-disrupting agent lisavanbulin (BAL101553) in treating ICI-resistant glioma." (PMID 40642066, 2025). "Anti-CSF-1R therapy by using CSF-1R inhibitors alone, such as PLX3397 (Plx, i.e., Pexidartinib) prominently extends animal survival, including long-term survival in previous preclinical glioma/GBM mouse models, which are far away from the results of anti-CSF-1R monotherapy in GBM clinical trials." (PMID 41365876, 2025). "Interestingly, glioma-secreted factors such as GM-CSF and IFN-gamma support macrophage survival in the presence of the CSF-1R inhibitor, although M2 macrophage polarization is significantly diminished." (PMID 40076738, 2025). "Furthermore, preclinical studies have shown that combining CSF1R and PD1 inhibition effectively counteracts the immunosuppressive tumor milieu in H3-mutant glioma." (PMID 40076738, 2025). "Congruently, pharmacological inhibition of CSF1R (BLZ945) in a PDGFB-driven GBM mouse model skewed macrophages to an immune-stimulating state blocking glioma progression and enhancing survival without depleting microglial cells." (PMID 38665919, 2024). "Despite these promising results, CSF1R inhibition has not demonstrated efficacy in pre-clinical and clinical glioma studies." (PMID 38665919, 2024).
glioma (continued). "These researchers observed that targeting these TAM populations using a CSF-1R inhibitor BLZ-945 in combination with RT could enhance the efficacy of RT and significantly improve survival in preclinical glioma models." (PMID 38474320, 2024). "CSF-1/CSF-1R is the essential signaling pathway for macrophage survival and proliferation, but the CSF-1R inhibitor BLZ945 suppresses glioma growth and progression by altering macrophage polarization, but not by depleting macrophages 104, and improves the survival rate of glioma mice." (PMID 37705736, 2023). "validated that the combination of CSF1R antibody 2G2 and PD-1 antibody altered the immune profile in tissues; particularly, it increased T cell infiltration and the ratios of CD8/CD4 and prolonged survival of mice with glioma." (PMID 37313405, 2023). "Nevertheless, a clinical trial using a CSF1R inhibitor in recurrent glioma patients did not increase survival." (PMID 35267626, 2022). "CSF-1R+ tumor cells, Iba1+ microglial cells at the periphery and infiltrating the glioma, and CSF-1R+, Iba1+ cells within the tumor mass were detected in nontreated animals." (PMID 35115369, 2022). "The CSF-1R inhibitor PLX5622 proves to have a disease-changing effect, reducing glioma progression and neuroinflammation, particularly when administered for a short period during established glioma growth." (PMID 35115369, 2022). "In addition, CSF-1R inhibition altered the polarization of macrophages via secreting GM-CSF and IFN-γ, which blocked glioma progression in a mouse model." (PMID 35585567, 2022). "Another CSF-1R inhibitor, PLX3397 (Pexidartinib), blocked growth of the murine proneural gliomas." (PMID 33809675, 2021). "Regarding CSF-1R/CSF-1 axis as a target for therapy, we have demonstrated that CSF-1R inhibition by PLX3397 affected more M2 than M1 macrophages, and induces their repolarization towards an M1-like phenotype, in accord with published results in glioma." (PMID 33731849, 2021). "In mice bearing glioblastoma multiforme or patient-derived glioma, BLZ945, a brain-penetrant kinase inhibitor targeting CSF-1R depolarizes M2 phenotype of TAMs, impairs their pro-tumor function and slows tumor growth that is associated with decreased M2 gene signatures." (PMID 34359674, 2021). "Interestingly, glioma cell invasion and microglial cell infiltration were reduced by PLX3397, a blocker of CSF-1R signaling." (PMID 34439380, 2021). "Although the CSF-1R inhibitor PLX3397 showed anti-tumor efficacy in a pre-clinical glioma model, these findings were not translated in recurrent glioblastoma patients." (PMID 31611871, 2019). "The same group recently demonstrated that long-term CSF1R inhibitor treatment led to acquired resistance driven by a compensatory IGF1–IGF1R signaling loop between macrophages and tumor cells, resulting in enhanced glioma cell survival and invasion." (PMID 29681904, 2018). "Besides IGF-1/PI3K signaling, several glioma cell-derived factors, such as GM-CSF and IFN-γ, seem to protect GAMs from CSF-1R inhibitor-mediated depletion and thereby mediate therapy resistance." (PMID 29389898, 2018). "Indeed, this idea has demonstrated effectiveness in the context of colony stimulating factor 1 receptor (CSF1R) inhibition, where GAMs can become “re-educated” within the glioma microenvironment to adopt an anti-tumorigenic phenotype." (PMID 32914058, 2018). "Further, CSF1R inhibition using the experimental compound PLX3397 has been shown to reduce disease progression and M2 gene signatures in preclinical models of glioma, and has enhanced efficacy over the broader spectrum tyrosine kinase inhibitors Vatalanib and Dovitinib." (PMID 32914058, 2018). "Other reports however suggest that anti‐CSF1R inhibitor appeared to re‐educate macrophages rather than decreasing their numbers in mouse glioma, correlating with tumor size reduction." (PMID 29038312, 2017).
glioma (continued). "A comparable phenotype shift was recently described in a glioblastoma model where inhibition of the CSF-1R reduced the glioma growth by qualitative but not quantitative effects on MC and MG." (PMID 26098772, 2015). "A recent study in pre-clinical GBM models showed that a specific inhibitor of CSF-1R did not deplete TAM but instead promoted their “re-education” via inhibition of M2-associated genes, resulting in hindered glioma growth and progression." (PMID 24202450, 2013). "Nine novel functional miRNAs (hsa-miR-129, -136, -145, -155, -181b, -342-5p, -342-3p, -376a/b) in GBM cell lines were validated for their importance in glioma cell growth, and similar effects for six target genes (ROCK1, RHOA, MET, CSF1R, EIF2AK1, FGF7) of these miRNAs were shown functionally." (PMID 23577178, 2013). "Interestingly, the quantity of TAMs themselves were not impacted by CSF-1R inhibition due to glioma-supplied factors that supported microglia survival." (PMID 38893093, 2024). "However, long-term treatment with CSF-1R inhibitors resulted in accumulation of IL4 released from other TME cell types which stimulated TAMs to secrete IGF-1 and conversely sustained the survival and growth of glioma cells." (PMID 38893093, 2024). "However, after prolonged treatment with CSF1R inhibitors, IL4 accumulated from other TME cell types stimulated TAMs to secrete insulin-like growth factor 1 (IGF1), which in turn sustains the survival and growth of glioma cells." (PMID 37190507, 2023). "After the inhibition of CSF‐1R, the authors observed a blockage in the growth and progression of the glioma, however, surprisingly this anti‐tumor effect was not mediated by the depletion of TAMs but rather by their re‐education within the glioma microenvironment." (PMID 36684102, 2023). "The role of the CSF-1/CSF-1R axis in tumor progression is of great importance not just for glioma." (PMID 34843542, 2021). "It would be interesting to examine if meaningful CSF1R antagonism could be achieved after exposure to radiation to test whether microglia have the ability to prune NGS, especially given their high abundance in glioma tissue." (PMID 33187183, 2020). "Therefore, the use of CSF1R and CSF1 inhibitors in glioma might have differential effects, as the downstream signaling events triggered by CSF1 and IL‐34 are distinct." (PMID 29038312, 2017). "ARRY-382 and GW-2580, innovative highly selective inhibitors of CSF1R, have demonstrated good tolerance and safety in clinical phase studies in patients with advanced or metastatic tumors but their effect in brain tumors such as gliomas has not yet been evaluated." (PMID 36555334, 2022). "Finally, it was shown that CSF-1R targeting by the BLZ945 inhibitor could lead to the switch of the TAM phenotype toward an anti-tumor phenotype in a glioma preclinical model thanks to GM-CSF and IFN-γ produced by glioma cells concomitantly to TAM depletion." (PMID 31547627, 2019). "CSF1–CSF1R signaling sustains TAM viability and skews polarization; in proneural glioma models, CSF1R blockade remodels rather than depletes TAMs and attenuates tumor growth, highlighting circuitry that can be pharmacologically reprogrammed." (PMID 41357191, 2025). "Moreover, CSF-1R overexpression did not induce AKT activation, but only ERK1/2 activity in glioma cells." (PMID 38254773, 2024). "In summary, recent preclinical mechanistic studies have indicated that the utilization of CSF-1R inhibition, such as through BLZ-945, as a standalone treatment for gliomas, may not be adequate to achieve a significant improvement in survival." (PMID 38474320, 2024). "In addition, treatment with CSF1R inhibitors such as AFS98 and BLZ945 increased the expression of M2 GAM markers, but they did not inhibit glioma growth as single agents." (PMID 36969167, 2023).
glioma (continued). "Similarly, the application of another anti-CSF-1R antibody, Emactuzumab (RG7155), also failed to achieve the therapeutic effect, likely due to reactive overproduction of IL-4 by glioma cells." (PMID 36969167, 2023). "Following CSF-1R inhibition, microglia and BMDM may not interfere with the benefits of initial radiotherapeutic tumour-debulking that leads to a significant delay in glioma recurrence." (PMID 36555253, 2022). "Furthermore, CSF-1 also regulates glioblastoma aggressiveness, with histological analysis of CSF-1R inhibitor-treated tumours revealing grade II and III glioma features, as opposed to the grade IV glioblastoma features seen in vehicle-treated mice." (PMID 33803414, 2021). "Interestingly, even though CSF1R-inhibition fails to deplete TAMs in this condition, profound phenotypic changes occur whereby the TAMs demonstrate an M1 expression signature and contribute to increased survival in murine PDGF-driven glioma models." (PMID 35267626, 2022).
glioblastoma (79 papers, 2013 to 2026). The most malignant astrocytic tumor (WHO grade IV). "For example, CSF/CSF-1R interactions have been shown to induce an immunosuppressive M2 phenotype in glioblastoma-associated microglia/macrophages, and blockade of CSF-1R improves survival in tumor-burdened mice." (PMID 39052000, 2024). "Noteworthy, IL-34 selectively bound PTPRZ1 in CSF-1R-deficient U251 human glioblastoma cells and led to an increase in the tyrosine phosphorylation of FAK and suppression of cell motility." (PMID 29796177, 2018). "Pre-clinical work in glioblastoma multiforme models has shown that macrophage ‘re-education’ through CSF1R inhibition caused re-polarization of TAMs towards an M1 phenotype, which dramatically increased survival, and regressed established tumors." (PMID 29731961, 2018). "However, while taking this into account, it may be that different glioblastoma subtypes (i.e., pro-neural glioblastoma) may be more susceptible to the reprogramming of monocytes/macrophages from CSF-1R inhibition." (PMID 31191529, 2019). "While our study demonstrates the promising potential of IL12/CSF1R‐MM‐IRC18‐LPS nanovesicles for NIR‐II fluorescence imaging‐guided membrane‐targeted mild photothermal‐immunotherapy of glioblastoma, several limitations should be acknowledged." (PMID 40279543, 2025). "More importantly, the targeted enrichment of CSF1R and IL12 in glioblastoma blocked the CSF1‐CSF1R signaling axis to promote M2‐to‐M1 repolarization and activated the antitumor T cell responses, respectively, which expedited the execution of glioblastoma." (PMID 40279543, 2025). "A switch from an anti-inflammatory to a pro-inflammatory phenotype has been found in myeloid cells treated with CSF-1R inhibitors that limit brain metastasis or intracranial growth, and similar findings have been reported in glioblastoma." (PMID 40760255, 2025). "Specifically, the CSF-1R inhibitor BIZ954 enhances glioblastoma responsiveness to radiotherapy and synergizes with anti–PD-1 immune checkpoint blockade, effectively augmenting antitumor immunity." (PMID 41479886, 2025). "The interaction between CSF‐1 and glial progenitor cells enhances the invasion of glioblastoma (GBM), while inhibition of CSF‐1R targeting glioma‐associated microglia may suppress GBM invasion." (PMID 40717900, 2025). "Nevertheless, a recent study investigated the possibility of reprogramming GAMMs to improve glioblastoma therapies by targeting the CSF-1R using three CSF-1R inhibitors, PLX3397, BLZ945, and GW2580, on GAMMs isolated from patient tumors." (PMID 39457693, 2024). "CSF-1R inhibition reduces tumor growth in several mouse models of cancer, including PyMT-driven mammary cancer, cervical cancer, glioblastoma and melanoma (119−121)." (PMID 39588367, 2024). "Previous studies have shown that CSF-1R inhibitors can impair tumor progression and decrease immunosuppressive macrophages in glioblastoma mouse models." (PMID 38443336, 2024). "In an animal model of glioblastoma, CSF-1R blockade demonstrated significant potential to reduce tumor growth, suggesting that CSF-1R inhibitors can block TAM-mediated immunosuppression and make tumor cells more susceptible to chemotherapeutics." (PMID 38033495, 2023). "One of the first studies to show that TAM re‐education within TME exerts an effect on tumor regression was reported in 2013, using a colony‐stimulating factor 1 receptor (CSF‐1R) inhibitor—called BLZ945—in multiple preclinical glioblastoma models." (PMID 36684102, 2023). "Macrophages rely on CSF1–CSF1R for survival and differentiation, and CSF1R inhibition suppressed glioblastoma progression both in vivo and in vitro, and, importantly decreased the macrophage M2 marker expression." (PMID 36494582, 2023). "Combinatorial strategies have also been explored in glioblastoma models where TAM populations where targeted with CSF1R inhibitor together with radiotherapy, enhancing survival of preclinical models." (PMID 35664746, 2022).